ENSG00000275163 (potassium large conductance calcium-activated channel, subfamily M, beta member 2 (KCNMB2-IT1 - KCNMB2 readthrough transcript))
Gene: Protein-coding gene on chromosome 3 (178,419,123 to 178,843,300, forward strand). Ensembl gene ENSG00000275163.
Genetic constraint (gnomAD): Loss-of-function variants: 6 observed, 20.22 expected, observed/expected ratio (o/e) 0.3, 90% interval 0.16 to 0.59. Missense variants: 196 observed, 262.48 expected, observed/expected ratio (o/e) 0.75, 90% interval 0.66 to 0.84. Synonymous variants: 97 observed, 99.67 expected, observed/expected ratio (o/e) 0.97, 90% interval 0.82 to 1.15.